OCLN (occludin)
Description:
May play a role in the formation and regulation of the tight junction (TJ) paracellular permeability barrier. It is able to induce adhesion when expressed in cells lacking tight junctions. (Microbial infection) Acts as a coreceptor for hepatitis C virus (HCV) in hepatocytes.
Synonyms: PPP1R115; BLCPMG; PTORCH1
Tractability: Antibody: UniProt places it where antibodies can reach, with high confidence; its Gene Ontology location is reachable by antibodies, with high confidence; UniProt predicts a signal peptide or a membrane-spanning region; the Human Protein Atlas places it where antibodies can reach. PROTAC: ubiquitination databases record sites on it; its protein half-life has been measured.
Gene: Protein-coding gene on chromosome 5 (69,492,184 to 69,558,104, forward strand). Ensembl gene ENSG00000197822.
Subcellular location: Cell membrane; Cell junction, tight junction
Subcellular location (Human Protein Atlas): Cell Junctions; Plasma membrane
Pathways (Reactome):
Developmental Biology: Epithelial-Mesenchymal Transition (EMT) during gastrulation
Gene expression (Transcription): RUNX1 regulates expression of components of tight junctions
Programmed Cell Death: Apoptotic cleavage of cell adhesion proteins
Gene Ontology:
Molecular function: protein binding; protein domain specific binding
Biological process: bicellular tight junction assembly; cell-cell junction organization; negative regulation of gene expression; positive regulation of blood-brain barrier permeability; positive regulation of D-glucose import; positive regulation of gene expression; regulation of D-glucose transmembrane transport; epithelial cell migration; maintenance of blood-brain barrier; positive regulation of lamellipodium assembly; positive regulation of microtubule polymerization; positive regulation of wound healing; protein localization to cell leading edge; protein-containing complex assembly; tight junction organization
Cellular component: bicellular tight junction; cell junction; cell-cell junction; cytoplasmic vesicle; lysosomal membrane; plasma membrane; protein-containing complex; tight junction; apical plasma membrane; cell leading edge; apicolateral plasma membrane; endocytic vesicle; membrane
Genetic constraint (gnomAD): Loss-of-function variants: 17 observed, 35.03 expected, observed/expected ratio (o/e) 0.49, 90% interval 0.33 to 0.73. The synonymous counts are far from expectation, so gnomAD's model fits this gene poorly and the ratio says little. Missense variants: 323 observed, 442.39 expected, observed/expected ratio (o/e) 0.73, 90% interval 0.67 to 0.8. Synonymous variants: 105 observed, 152.24 expected, observed/expected ratio (o/e) 0.69, 90% interval 0.59 to 0.81.
Homologues: Orthologues: chimpanzee OCLN (99% identical), macaque OCLN (92% identical), mouse Ocln (90% identical), rabbit OCLN (90% identical), dog OCLN (89% identical), rat Ocln (89% identical), guinea pig OCLN (89% identical), pig OCLN (89% identical), tropical clawed frog ocln (52% identical), zebrafish oclna (44% identical), zebrafish oclnb (39% identical), Drosophila melanogaster Su(Tpl) (13% identical), and 1 more. Paralogues in human: ELL (17% identical), ELL2 (17% identical), MARVELD2 (16% identical), ELL3 (11% identical), OCEL1 (9% identical).
Diseases named in the same sentence as OCLN in open-access papers:
OCLN is named in the same sentence as 362 diseases in open-access papers, as found by Europe PMC text mining. Sharing a sentence is not in itself a finding about the gene and the disease. The quoted sentences say what the papers report.
colitis (359 papers, 2007 to 2026). Inflammation of the colon. "IBD induces intestinal barrier dysfunction by reducing the expression of TJ proteins (Claudin-1, Occludin, and ZO-1) in colonic tissues, which consequently increases susceptibility to colitis." (PMID 40883849, 2025). "Immunofluorescence and western blotting showed that the protein expression levels of the intestinal barrier-associated proteins ZO-1 and occludin were significantly lower in the colonic mucosa of DSS-induced colitis mice than in normal mice." (PMID 40969742, 2025). "Studies showed that α and γ tocopherols inhibited colitis-induced occludin loss and reduced the plasma levels of LPS-binding proteins, which protected intestinal barrier integrity, as shown by a DSS-induced colitis mouse model." (PMID 39339792, 2024). "In DSS-caused colitis, vitamin E regulates the expression of occludin and alleviates the symptoms of colitis." (PMID 38540888, 2024). "Multiple studies have shown that colitis patients altered TJ structure in intestinal epithelium, with significant downregulation of TJ proteins occludin and ZO-1, causing the increase in intestinal permeability." (PMID 38998101, 2024). "Previous studies have shown that declining levels of E-cadherin and Occludin are significantly associated with the intensity of colitis." (PMID 38245781, 2024). "Previously, propionate has been demonstrated to ameliorate dextran sodium sulphate-induced colitis in murine models by increasing expression of tight cell junction (TCJ)-associated proteins (e.g. Zona occludin, E-cadherin)." (PMID 38662018, 2024). "Decreased expression of tight junction (TJ) proteins such as ZO-1 and Occludin can weaken the intestinal epithelium integrity and cause colitis." (PMID 37237988, 2023). "Notwithstanding, these proteins are susceptible to colitis and reduced expression and function of epithelial occludin have been found in IECs of UC patients." (PMID 36707899, 2023). "In other words, Polycan has a protective effect on intestinal length shortening with weight loss in DSS-induced colitis mice and intestinal permeability, by regulating adhesion proteins (e.g., ZO-1, occludin, and claudin-2)." (PMID 37834221, 2023). "Surprisingly, mice with DSS-induced colitis who were administered HS showed normalized the expression levels of ZO-1, occludin and claudin-1, which are interepithelial TJ-associated proteins that play pivotal roles in gut homeostasis." (PMID 35025709, 2022). "Previous studies reported altered expression or loss of TJ proteins occludin and ZO-1 and reduced mucin expression in colitis patients and in mouse models of intestinal inflammation, which the present study confirmed." (PMID 34497514, 2021). "And we found that NLRP3 deficiency aggravates DSS-induced colitis by exacerbating gut structure and tight junction (Occludin)." (PMID 32950971, 2020). "Loss of Zo-1, claudin-1, and occludin in Caco-2 cells and the colitis tissues was recovered after PRCC-1301 EVs treatment, as evidenced by immunofluorescence analysis." (PMID 33233771, 2020). "Intestinal mucosal barrier destruction was associated with colitis progression; additionally, junction protein expression (occludin, ZO-1, and claudin-4) in the colon was determined by quantitative PCR and immunofluorescence." (PMID 31632373, 2019). "It was found that KIOM-2015E repaired the expression of tight junctions and its associated protein ZO-1 and occludin in the treatment and prevention of colitis diseases." (PMID 30402509, 2018). "EtOH feeding or DSS-induced colitis caused a reduction of junctional stain for occludin and ZO-1, and the loss of stain for these tight junction proteins was more severe when EtOH feeding was combined with colitis." (PMID 30389960, 2018). "It was found that sodium propionate increased the serum FITC-dextran level and inhibited the down-regulation of tight junctions and its associated protein occludin, E-cadherin, and ZO-1 in the colon of colitis mice." (PMID 27574508, 2016).
colitis (continued). "In line with our observations, recent data in colitis associated impaired barrier function indicated that alterations in the expression level and localization of occludin are pivotal for increased paracellular permeability." (PMID 21977944, 2011). "Following DSS, M. elsdenii aggravates colitis in GF mice, demonstrated by greater weight loss, higher disease activity score and spleen index, more severe colonic pathological score, shorter colon length and lower expressions of Zo‐1 and Occludin." (PMID 40801433, 2025). "HD could also reduce the levels of FITC-Dextran, DAO, ET, and D-LA and increase the expression of ZO-1, occludin, and E-cadherin in the colonic tissues of colitis mice, thereby maintaining the impaired intestinal barrier function caused by colitis." (PMID 39650157, 2024). "The loss of ZO-1 and occludin genes has been reported in DSS-induced colitis mouse models." (PMID 34395495, 2021). "However, colitis often caused gut barrier damage by reducing the expression of TJ proteins zonula occludens-1 (ZO-1), occludin, and claudin-1." (PMID 35059326, 2021). "We showed that metformin alleviated dextran sodium sulphate (DSS)‐induced decreases in transepithelial electrical resistance, FITC‐dextran hyperpermeability, loss of the tight junction (TJ) proteins occludin and ZO‐1 and bacterial translocation in Caco‐2 cell monolayers or in colitis mice models." (PMID 29148173, 2018). "In summary, we suggest that expressions of TJ proteins Occludin and Claudin-1 in the large intestinal epithelium are under control of the circadian clock, which is associated with temporal changes of colonic permeability and also susceptibility to colitis." (PMID 24845399, 2014). "Occludin and Claudin-1 expressions in the large intestine are under the circadian control, which is associated with temporal regulation of colonic permeability and also susceptibility to colitis." (PMID 24845399, 2014). "To investigate whether the susceptibility of CerS4 KO mice to DSS-induced colitis was related to a colon barrier dysfunction, we detected the expression of tight-junction proteins occludin and zonula occludens-1 (ZO-1) in the colon tissue of CerS4 WT and CerS4 KO mice." (PMID 35163788, 2022). "Immunofluorescence staining and its quantification results showed that in the DSS‐induced colitis mouse model group, the expression of ZO‐1, E‐Cadherin, and Occludin in colon lesion tissues was significantly downregulated." (PMID 41244343, 2025). "AMK polysaccharides increase the expression of tight junction proteins, such as ZO-1, Occludin, and Claudin-1, to strengthen the intestinal epithelial barrier in patients with conditions such as colitis and diarrhea." (PMID 40144663, 2025). "Previous reports have shown that kombucha supplementation improves the mRNA expression of MUC2, occludin, claudin‐1, ZO‐1, and ZO‐2 in mice models of colitis and type 2 diabetes." (PMID 40822525, 2025). "After 7 days of DSS-induced colitis, the expression of occludin and ZO-1 in the colon was markedly reduced." (PMID 40371345, 2025). "Losartan has been shown to reduce IP in TNBS-induced colitis mice, enhance OCLN and ZO-1 gene expression lowering circulating LPS in SHR, and decrease colonic permeability in LPS-treated Sprague-Dawley rats." (PMID 41515345, 2025). "A previous study also demonstrated that TSG enhances barrier function by upregulating ZO-1 and occludin expression in a dextran sulfate sodium (DSS)-induced colitis model." (PMID 41516109, 2025). "C9orf72 overexpression attenuated DSS‐induced colitis and the intestinal epithelial barrier disorder by promoting the expression of ZO‐1 and Occludin." (PMID 39873292, 2025). "In mice and patients with colitis, elevated IL-1β and MIR200C-3p levels correlate with reduced occludin and increased TJ permeability, a hallmark of intestinal inflammation." (PMID 40801578, 2025).
colitis (continued). "In the DSS colitis mouse model, liraglutide-treated mice exhibited significantly lower caecal occludin mRNA levels and higher TNF-α mRNA levels compared to controls, while RegIIIβ and IL-33 mRNA levels showed an increased trend." (PMID 40426955, 2025). "For example, red bean extracts alleviated DSS-induced acute colitis by reducing inflammation and restoring OCLN expression." (PMID 41614862, 2025). "In a previous study, L. gasseri JM1 showed the effect of alleviating the damaged barrier structure by increasing the expression of claudin-3, occludin, and ZO-1 and regulating inflammatory and anti-inflammatory cytokines in a mouse model of colitis." (PMID 40002326, 2025). "To examine the therapeutic effects of NAF AuNRs on epithelial barrier function in colitis, we analyzed the expression of ZO-1, claudin-1, and occludin, the critical components of TJs, by RT-PCR, WB, and IF." (PMID 40255504, 2025). "Immunofluorescence of tight‐junction proteins ZO‐1 and occludin showed reduced expression in Nr1d1−/− colons during colitis, consistent with impaired barrier integrity." (PMID 41163542, 2025). "Targeting MIR200C-3p with an antagonist preserves occludin expression, reduces permeability, and mitigates barrier dysfunction, offering potential therapeutic benefits for colitis." (PMID 40801578, 2025). "The protein levels of ZO‐1 and Occludin were extensively increased in mice with colitis after C9orf72 injection." (PMID 39873292, 2025). "In mice with DSS-induced colitis, the amounts of occludin and claudin-1 in their colon tissue dropped noticeably." (PMID 41247018, 2025). "For instance, oral administration of SB extract (SBE) enhanced the expression of tight junction proteins ZO-1 and occludin in a rat model of colitis." (PMID 41145081, 2025). "In summary, the KMLE effect in a DSS-induced colitis mouse model and Caco-2 cells works by suppressing the inflammatory-related chemokine levels and recovering the protein levels of ZO-1 and OCLN." (PMID 40227441, 2025). "The findings suggest VIS improves occludin expression and mitigates inflammatory responses, highlighting its potential as a therapeutic agent for colitis." (PMID 40502390, 2025). "It was observed that ligustilide protected the colonic microvilli structure, narrowed the tight junction gap, and enhanced tight junction protein Claudin-1 and Occludin expressions in colitis mice." (PMID 40904624, 2025). "In our study, ZO‐1 and Occludin expression were enhanced in mice with colitis after C9orf72 injection." (PMID 39873292, 2025). "DSS-induced colitis decreased the expression of intestinal tight junction proteins such as Occludin, Claudin-1, and ZO-1." (PMID 40842836, 2025). "C9orf72 overexpression in mice attenuated DSS‐induced colitis and intestinal epithelial barrier damage by stimulating ZO‐1 and Occludin expression." (PMID 39873292, 2025). "Consistent with this, our earlier research also confirmed that VK supplementation elevated occludin, claudin-1, and ZO-1 expression in colitis mice." (PMID 41334343, 2025). "Consistent results were confirmed through western blot analysis, demonstrating that SC reversed the downregulation of ZO-1 and Occludin proteins expression in colitis mice." (PMID 39936162, 2025). "Similar protective effects have been observed with Enalaprilat, which preserved ZO-1 localization and prevented OCLN internalization while reducing FITC-dextran flux in dextran sodium sulfate (DSS)-induced colitis mice." (PMID 41515345, 2025). "Mulberry anthocyanins alleviated colonic tissue damage and the inflammatory reaction in DSS-induced colitis mice and maintained the intestinal barrier by restoring the levels of intestinal tight junction (TJ) proteins (claudin-3, occludin, and ZO-1)." (PMID 39947703, 2025). "EPS produced by L. plantarum NMGL2 restored epithelial integrity in DSS-induced colitis, increasing the expression of tight junction proteins ZO-1 and occludin and suppressing NF-κB p65 activation." (PMID 41373958, 2025).
colitis (continued). "This barrier is maintained by tight junction proteins such as ZO-1, Occludin, and Claudins, which, when damaged, lead to increased intestinal permeability and exacerbate inflammation, hallmarks of colitis." (PMID 41196878, 2025). "Berberine in DSS colitis models has been shown to increase the colonic expression of ZO-1, ZO-2, occludin, and E-cadherin, correlating with reduced mucosal permeability." (PMID 41008518, 2025). "A recent study using a DSS colitis mouse model showed, that EGCG stimulates the mRNA expression of the TJ protein occludin and the TJ-associated scaffold protein ZO-1." (PMID 40438590, 2025). "In DSS colitis mice, puerarin treatment increased colonic ZO-1 and occludin levels and prevented the rise in the intestinal permeability, which is consistent with a more intact barrier." (PMID 41008518, 2025). "After Cramp treatment, the reduced expressions of occludin proteins were counteracted, which provided another strong evidence for the protective effects of Cramp against colitis in mice." (PMID 38380090, 2024). "By detecting the expression levels of tight junction proteins Occludin and ZO-1 mRNA in the colon, we can understand how heat-killed S. boulardii affects the regulation of tight junction proteins in colitis mice." (PMID 38474831, 2024). "Meanwhile, colonic TJ proteins ZO-1, MUC2, claudin-1, and occludin in colitis mice pre-treated with B. tequilensis YB-2 significantly increased their expression levels and played a critical part in maintaining the epithelial barriers of the mouse colon." (PMID 38998101, 2024). "The protein levels of MPO, ZO-1, E-cadherin, and occludin were decreased in acute and chronic colitis model mice after LM-CsA NP treatment, and intestinal function recovered after treatment." (PMID 39512421, 2024). "IL-1β can down-regulate the mRNA level of occludin and increase intestinal TJ permeability, all of which are related to the onset and deterioration of colitis symptoms." (PMID 39452928, 2024). "The results revealed a lower percentage of brownish-yellow areas corresponding to Claudin-1, ZO-1, and Occludin in the Gpr81−/− colitis mice, indicating a reduced expression of TJ proteins." (PMID 38474712, 2024). "And consistent with our in vitro and mouse colitis model, occludin 3-Cl-Tyr from individuals with active UC was significantly increased compared with healthy controls (P < 0.0001)." (PMID 39133648, 2024). "Treatment with an IL-17A antibody leads to the diffusion of occludin, compromising intestinal integrity, increasing gut permeability, facilitating pathogen invasion, and ultimately exacerbating colitis through the altered localization of occludin." (PMID 39379604, 2024). "Immunohistochemical (IHC) analysis of the tight junction (TJ) proteins ZO-1 and occludin was conducted to investigate their expression levels in the colitis mice model." (PMID 38613088, 2024). "This compound increased occludin and claudin-1 expression, ameliorated goblet cell damage in mice with colitis, and promoted mucus secretion, allowing it to maintain intestinal physical and chemical barrier integrity." (PMID 39339792, 2024). "In conclusion, our findings suggest that CSCC treatment can protect mice from DSS-induced colitis by upregulating Gpr43, promoting the expression of ZO-1 and Occludin tight junction proteins." (PMID 39329121, 2024). "Specifically, DSS-induced colitis markedly decreased the expression of ZO-1, occludin, and claudin-1 and dramatically increased the expression of claudin-2 at the mRNA levels; nevertheless, the abnormal expression was corrected by the UTI treatment." (PMID 38397811, 2024). "CSCC protected mice from DSS-induced colitis by upregulating Gpr43, promoting the expression of ZO-1 and Occludin tight junction proteins." (PMID 39329121, 2024).